FGF19 (fibroblast growth factor 19)
Diseases named in the same sentence as FGF19 in open-access papers (continued):
Sharing a sentence is not in itself a finding about the gene and the disease.
breast cancer (continued). "Our present data revealed that the FGF-19 levels were twice as high in breast cancer and tripled in dense breast tissue, compared with the normal tissues within each cohort, suggesting that FGF-19 may be a clinically relevant protein to target also in human breast tissue." (PMID 29387062, 2017). "Importantly, the co-expression of FGFR4/FGF19 is significantly associated with AKT phosphorylation, Ki-67 staining, higher tumor stage and basal-like phenotype (triple-negative and CK5/6 positivity) in breast cancers." (PMID 27192118, 2016). "In silico data from computational docking of FGF19 and BCL-2 proteins showed that they play significant roles in hepatocellular and breast cancer development, respectively." (PMID 39334936, 2024). "Prolonged estrogen deprivation in breast cancer cells can lead to upregulation of FGFR1 together with FGF3, FGF4, and FGF19 due to co-amplification of the FGFR gene and genes located in the 11q13 region." (PMID 38255923, 2024). "In a Phase 1/2a study of patients with breast carcinoma harboring an amplification of FGFR1, FGF3, FGF4, or FGF19, lucitanib resulted in a disease control rate (DCR) of 100%; 50% (6/12) of patients achieved PR and 50% (6/12) of patients had SD." (PMID 38380359, 2024). "This chromosomal region is amplified simultaneously with the 11q12–14 region, which contains other oncogenes with a role in breast cancer progression, like CCND1, FGF3, FGF4 and FGF19." (PMID 35193394, 2022). "The FGF19/FGFR4 axis has been connected to dismal patient prognosis and disease progression in different tumor entities including HCC and breast cancer." (PMID 35484633, 2022). "For example, amplification of the FGF19 genomic locus including the well-established proto-oncogene CCND1, was found in liver cancer, breast cancer, lung cancer, bladder cancer and esophageal cancer." (PMID 32154250, 2020). "CNAs in CCND1, FGF3, FGF4, and FGF19, which are all located in the q-arm of chromosome 11 were more likely to be detected from patients with HR+/HER2+ and HR+/HER2− breast cancer (P < 0.001)." (PMID 32695676, 2020). "siRNA-mediated silencing of FGF19 or neutralization of extracellular FGF19 by anti-FGF19 antibody (1A6) decreases AKT phosphorylation, suppresses cancer cell growth and enhances doxorubicin sensitivity only in the FGFR4+/FGF19+ breast cancer cells." (PMID 27192118, 2016). "Besides, FGFR4 drives basal-like breast cancer cell survival through PI3K/AKT activation, with a subset relying on FGF19-mediated autocrine signaling." (PMID 41210688, 2025). "Although alterations in KMT2C and FGF19 are common in breast cancer, there is currently no clinical evidence of the correlation between them and the therapeutic effect of breast cancer." (PMID 40994809, 2025). "Consequently, these findings further support a role of FGFR4 in GBM recurrence in a highly aggressive GBM subset based on an autocrine loop connecting FGF19 and FGFR4, as previously reported in breast cancer." (PMID 35484633, 2022). "Since FGFR4 upregulation and activation has been recently shown to confer chemoresistance in breast cancer cells, we asked whether inhibition of the FGFR4/FGF19 axis might enhance chemotherapy sensitivity in cancer cells." (PMID 27192118, 2016). "Our results show that the basal-like breast cancer cell lines express high levels of secreted FGF19 as compared to luminal-like breast cancers or non-transformed mammary myoepithelial cells." (PMID 27192118, 2016). "Finally, to determine whether FGFR4/FGF19 co-expression is present in primary breast tumors, we stained tissue microarrays of primary human breast cancer samples diagnosed with invasive ductal carcinoma (IDC) for FGFR4 and FGF19, and compared this with AKT phosphorylation." (PMID 27192118, 2016).
breast cancer (continued). "Inhibition of FGFR4/FGF19 autocrine axis enhances doxorubicin, but not cisplatin or paclitaxel, sensitivity in MDA-MB-468 and HCC1937 breast cancer cells, suggesting that the anti-FGF19 monoclonal antibody might potentiate sensitivity of refractory tumor cells to chemotherapy." (PMID 27192118, 2016).
Hepatic steatosis (32 papers, 2013 to 2025). Steatosis is a term used to denote lipid accumulation within hepatocytes. "Similar to the aggravation of liver steatosis, mRNA expression levels of genes associated with lipid synthesis, lipid transport and inflammation were increased in the liver of FGF19-treated Piezo1ΔIEC mice." (PMID 39781454, 2025). "Low levels of FGF19 were associated with hepatic steatosis, especially in patients with high levels of anti-tTG antibodies." (PMID 35208205, 2022). "Dysregulation of FGF19 contributes to many metabolism-associated diseases, such as fatty liver disease and type 2 diabetes." (PMID 36532504, 2022). "Although the role and mechanism of FGF15/19 played in liver steatosis was still ambiguous, we confirmed that FGF15 reduction mediated the amelioration of liver steatosis caused by PIEZO1 deficiency by applying FGF19 supplementary experiment in HFD-fed Piezo1ΔIEC mice." (PMID 39781454, 2025). "After supplementary of exogenous FGF19, the effect of improving liver steatosis brought by PIEZO1 deletion was blocked." (PMID 39781454, 2025). "Conversely, FGF19 administration improves glucose homeostasis and hepatic steatosis, with recent clinical trials reporting promising results." (PMID 41303064, 2025). "The overexpression of FGF19 can improve the accumulation of liver lipids and alleviate fatty liver by attenuating the expression of sterol regulatory element-binding protein 1c and ACC in the liver." (PMID 41114583, 2025). "We also measured FGF-19, which has been shown in animal studies to have beneficial effects on glucose homeostasis and on hepatic steatosis." (PMID 38892505, 2024). "Reduced circulating FGF19 was found in subjects with metabolic disorders and hepatic steatosis, and FGF19 analogues have been identified as promising therapeutic methods in metabolic improvement." (PMID 35909556, 2022). "The study showed that cilofexor was safe and associated with significant attenuation of hepatic steatosis (lipid accumulation), liver enzymes (AST, ALT, and GGT), and bile acids synthesis without any significant alteration of fasting plasma levels of FGF19." (PMID 36500979, 2022). "UDCA was reported to improve hepatic steatosis by reducing circulating fibroblast growth factor 19 and blunting farnesoid X receptor activation, which effectively alleviated hepatic steatosis." (PMID 35833020, 2022). "The effects of FGF-19 in the liver involve suppression of de novo lipogenesis, increase of fatty acids oxidation, and suppression of bile acids synthesis; thereby, FGF-19 is thought to ameliorate hepatic steatosis and lipotoxicity." (PMID 32069846, 2020). "We hope to elucidate the roles of bile acids and FGF 19 and offer mechanistic insights into human DM remission and fatty liver improvement." (PMID 31181641, 2019). "FGF 19 is a peptide with 216 amino acids and was proposed as a metabolic regulator in improving DM, hyperlipidemia, hepatic steatosis, and adiposity." (PMID 31181641, 2019). "Overexpression of FGF19/FGFR4 significantly correlated with EpCAM as a marker of hepatic cancer stem cells within the fatty liver-steatosis-cirrhosis-HCC sequence." (PMID 27447573, 2016). "Particularly, authors observed that low levels of Fibroblast Growth Factor 19 (FGF-19), normally repressed in CD patients on a GFD, and anti-tTG positivity are associated with a higher prevalence of hepatic steatosis, supposing a direct role of BAs in hepatic steatosis pathogenesis." (PMID 36675276, 2023). "FGF19 circulating levels can either decrease or increase in extrahepatic cholestasis, inflammatory bowel disease, kidney disease, BA malabsorption, obesity, and liver steatosis." (PMID 36500979, 2022). "As the DM-CR and FL-I groups both exhibited significantly decreased total bile acid levels and increased FGF 19 levels 1 year after SG, plasma total bile acids and FGF 19 then might have some roles in DM remission and fatty liver improvement." (PMID 31181641, 2019).
Hepatic steatosis (continued). "In addition, our study suggests that the preoperative FGF 19 levels ≤ 49.97 pg/mL have a predictive role in fatty liver improvement 1 year after surgery." (PMID 31181641, 2019). "Our serum FGF19 data consist to expressions of FGF19/FGFR4 and EpCAM in tissue distributions, and provide further evidence for FGF19 as a marker to evaluate the risk of HCC in patients with fatty liver disease." (PMID 27447573, 2016). "Further, the FL-I group had significantly lower total bile acid levels, lower gamma glutamyl transferase levels, and FLI at M12 than at MBased on these results, total bile acid and FGF 19 might have some roles in DM remission and the fatty liver improvement one year after SG." (PMID 31181641, 2019). "In animal models, the administration of FGF19 and FGF21 improves insulin sensitivity, lipid levels, and liver steatosis while ameliorating body weight and fat mass." (PMID 38891828, 2024). "In atherosclerosis, both FGF19 and NGM282 regulated cholesterol homeostasis and improved hepatic steatosis in db/db mice." (PMID 35847588, 2022). "Overexpression of FGF19 and both systemic and intestinal-specific activation of FXR have been shown to ameliorate hepatic steatosis and inflammation in ethanol-fed mice." (PMID 35456053, 2022). "Plasma FGF 19, FGF 21, and total bile acid levels were measured before surgery (M0), 3 months (M3), and 12 months (M12) after surgery, while the hepatic steatosis index (HSI) was calculated before and after surgery." (PMID 35277004, 2022). "In Phase 2 clinical trials analogues of FGF19 and FGF21 decrease hepatic steatosis with up to 70% (MRI-PDFF) after 12 weeks and as early as 12–16 weeks of treatment an improvement in NASH resolution and fibrosis has been observed." (PMID 33414764, 2020). "FGF19 requires KLB expression in the liver to regulate Cyp7a1 expression in mice, while the positive effect of FGF19 and FGF21 on hepatic steatosis was unaffected by adipose and liver specific KLB deletion." (PMID 33414764, 2020). "Here, we report that FGF19 and NGM282 promote HDL biogenesis and cholesterol efflux from the liver by selectively modulating LXR signaling while ameliorating hepatic steatosis." (PMID 30679232, 2019). "The IHC results demonstrated significant increases of protein expressions of FGF19, FGFR4 and EpCAM in specimens with fatty liver, NASH, cirrhosis, and HCC compared to healthy liver tissue." (PMID 27447573, 2016). "Major biomarkers in our index are FGF21, FGF19 and A/L, which have not been used in previous biomarker panels for the prediction of fatty liver." (PMID 35663311, 2022). "Treatment with the clinical candidate, obeticholic acid reversed the hepatic steatosis phenotype and transcriptomic analysis confirmed the selective activation of FXR target genes including upregulation of FGF19 and PLIN1 and downregulation of SLC51B and CYP7A1 genes by OCA." (PMID 33334026, 2020). "FGF19 and FGF21 both depend on KLB expression in the CNS to lower hepatic steatosis." (PMID 33414764, 2020). "In particular, both FGF19 and its analog, NGM282, selectively activate LXR signaling pathways in the liver to enable anti-inflammatory and anti-atherosclerotic responses, while ameliorating hepatic steatosis." (PMID 30679232, 2019). "In addition to this, FGF19 (the human ortholog of FGF15) has been suggested to improve adiposity and liver steatosis in obese mouse models and the mouse Fgf15 gene has been defined as a direct transcriptional target of VDR." (PMID 30609782, 2019). "The aim of this study is to investigate the molecular components of the signaling pathways that are responsible for the development and progression of HCC and to provide the evidence for the clinical activity of FGF19, FGFR4, and EpCAM in patients with HCC arising from fatty liver disease." (PMID 27447573, 2016).
Hepatic steatosis (continued). "However, hepatic steatosis was ameliorated, rather than increased, following FGF19 or NGM282 treatment of db/db mice, despite increases in Srebf1, Fasn, and Scd1 mRNA levels." (PMID 30679232, 2019). "DHA-CHO-VE supplementation improved severe hepatic steatosis (ranging 5-50%, p=0.001); ALT and fasting glucose levels.DHA-CHO-VE supplementation did not influence bile acid levels, while increased intestinal FGF19 compared to placebo." (PMID 40821837, 2025). "FGF19 and FGF21 are also considered as predictors of development of some diseases, for example, type 2 diabetes, non-alkoholic fatty liver disease, atherosclerosis, coronary artery disease, and chronic kidney disease." (PMID 30927227, 2019). "Thus, FGF19 and NGM282 appear to selectively modulate LXR signaling, upregulating canonical LXR target genes (Abcg5, Abcg8, Scarb1, Srebf1, Fasn, Scd1, Srebf2, and Scap) without inducing hepatic steatosis." (PMID 30679232, 2019).
type 2 diabetes (31 papers, 2011 to 2026). "For instance, the identification of reduced FGF-19 or FGF-22 levels in overweight individuals or those with type 2 diabetes could indicate a higher risk of metabolic decompensation and musculoskeletal deterioration." (PMID 40943671, 2025). "In conclusion, elevated serum FGF-19 levels post-surgery were significantly associated with improved mitochondrial health in AT, leading to greater control of mitochondrial gene regulation and overall type-2 diabetes remission." (PMID 28202005, 2017). "Our findings suggest that total cBAs and FGF-19 have potential as biomarkers of insulin sensitivity that should be considered for future studies investigating the mechanism underlying glucose metabolism alterations predicting Type 2 diabetes risk and its sequelae." (PMID 41169463, 2025). "One previous study indicated FGF19 levels were significantly lower in subjects with impaired fasting glucose and type 2 diabetes than in those with normal glucose tolerance." (PMID 41522208, 2026). "FGF-21, known to regulate glucose and lipid metabolism, was previously reported to correlate positively with triglycerides in type 2 diabetes; a similar relationship with triglycerides was observed in our study for FGF-19 and FGF-22." (PMID 40943671, 2025). "The results of this study align with existing literature on the protective role of FGF-19 in the development of type 2 diabetes." (PMID 41169463, 2025). "Intestinal Akkermansia muciniphila is depleted in lean individuals with type 2 diabetes, who have increased 3β‐chenodeoxycholic acid (βCDCA), reduced insulin secretion and fibroblast growth factor 19 (FGF19) expression." (PMID 34085773, 2021). "Decreased circulating FGF19 levels have been reported in obese, insulin resistant and type 2 diabetes patients." (PMID 35145481, 2021). "FGF19 is also associated with type 2 diabetes mellitus (T2DM)." (PMID 34572066, 2021). "This study aimed to evaluate the relationship between the levels of serum FGF19 and endogenous islet beta cell function in type 2 diabetic patients." (PMID 31572498, 2019). "In human metabolic syndrome associated diseases, such as type 2 diabetes mellitus (T2DM) and NAFLD, FGF19 signaling seems to be dysregulated." (PMID 29866129, 2018). "Sonne and colleagues found that FGF19 concentrations in patients with type 2 diabetes and healthy controls increased with increasing fat and decreasing carbohydrate content in liquid meals (500 kcal, 2.5 vs. 10.0 and 40.0 g fat)." (PMID 29866129, 2018). "We recently showed that FGF19 serum levels are decreased and bile acid levels increased in patients with type 2 diabetes." (PMID 24465600, 2014). "It was found that fibroblast growth factor 19 levels, known to have a protective effect on atherosclerosis in patients with type 2 diabetes, are down-regulated by OSA, thus weakening their protective effect and exacerbating outcomes, consistent with prior research." (PMID 39351220, 2024). "Circulating FGF19 and insulin concentrations are positively correlated in patients with type 2 diabetes, suggesting that FGF19 may participate in insulin-dependent glucose regulation." (PMID 35145481, 2021). "The aim of this study was to investigate the association of HOMA-IR with fasting, circulating BA levels in participants with and without type 2 diabetes, and to evaluate the role of FGF-19 in this association, in a general population of Italian elderly from the RoCAV cohort." (PMID 41169463, 2025). "Consistent with our findings, a recent study showed that exogenous administration of the FGF19 analog NGM282 did not correct hyperglycemia in patients with type 2 diabetes (T2D) but instead caused a rapid and sustained reduction in hepatic Cyp7a1 levels and liver fat content in patients with MASLD." (PMID 38587078, 2024).